FASN (fatty acid synthase)
Diseases named in the same sentence as FASN in open-access papers (continued):
Sharing a sentence is not in itself a finding about the gene and the disease.
medulloblastoma (5 papers, 2012 to 2025). A malignant, invasive embryonal neoplasm arising from the cerebellum. "The enzyme fatty acid synthase (FASN), which catalyzes de novo lipid synthesis, is often upregulated in medulloblastoma, particularly in subtypes with high proliferative indices." (PMID 40868156, 2025). "Since lipid metabolism is less active in normal brain cells compared to medulloblastoma cells, FASN inhibitors hold promise as selective metabolic interventions for targeting tumor cells." (PMID 40868156, 2025). "Orlistat, an FASN inhibitor initially approved as an anti-obesity drug, has shown anti-tumor activity in preclinical medulloblastoma models by blocking fatty acid synthesis and inducing cell death." (PMID 40868156, 2025). "In more recent work, we demonstrated that excessive mitogenic signaling by Shh, a driver of medulloblastoma, engages the Rb/E2F tumor suppressor complex, activates the key enzyme fatty acid synthase (FASN) and drives lipogenesis through a novel, E2F1-regulated process." (PMID 22407012, 2012). "We next examined whether in medulloblastomas expression of PPARγ, like that of FASN, requires E2F1 activity." (PMID 22407012, 2012). "Similarly, in medulloblastoma, FASN-driven lipid synthesis sustains tumor proliferation." (PMID 40370434, 2025).
oral cancer (5 papers, 2017 to 2024). "In summary, this study demonstrated that P. gingivalis stimulated 4NQO-induced oral cancer and altered FFA metabolism in blood and tongue tissues of 4NQO-induced mice, which may involve in de novo FA synthesis pathways by upregulating the expression of FASN and ACC1." (PMID 30233549, 2018).
renal carcinoma (5 papers, 2015 to 2025). A carcinoma arising from the epithelium of the renal parenchyma or the renal pelvis. "Further, using a pharmacological inhibitor of fatty acid synthase has been shown to suppress growth and invasiveness of renal cancer cells." (PMID 36516496, 2022). "Moreover, pharmacological inhibitors of fatty acid synthase could suppress the growth and invasiveness of renal cancer cells." (PMID 40591061, 2025).
renal cell carcinoma (5 papers, 2019 to 2025). "A previous study found that fatty acid synthase is significantly downregulated in obese patients with renal cell carcinoma and is associated with favorable survival outcomes." (PMID 31226155, 2019). "In renal cell carcinoma, it was shown that obese patients were less likely to present with an advanced stage owing to downregulation of fatty acid synthase." (PMID 35802728, 2022). "Molecular docking findings indicate that the environmental endocrine-disrupting chemical BPA specifically interacts with key targets essential for the function of renal cell carcinoma cells, including CHRM3, GABBR1, CCR4, KCNN4, PRKCE, CYP2C9, HPGD, and FASN." (PMID 41301871, 2025).
acute lymphoblastic leukemia (4 papers, 2020 to 2024). Leukemia with an acute onset, characterized by the presence of lymphoblasts in the bone marrow and the peripheral blood. "In another study, molecular modeling analysis suggested that isogingerenone may bind to the fatty acid synthase enzyme, a marker protein in acute lymphoblastic leukemia." (PMID 37754674, 2023).
alcoholic fatty liver disease (4 papers, 2018 to 2024). Lipid infiltration of the hepatic parenchymal cells that is due to alcohol abuse. "Data from phase I clinical trial corroborate that TVB‐2640, a FASN inhibitor, restrains the uptrend of hepatic de novo lipogenesis and thus emerges as a novel therapeutic avenue for non‐alcoholic fatty liver disease." (PMID 33665967, 2021).
bone cancer (4 papers, 2015 to 2024). A primary or metastatic malignant neoplasm affecting the bone or articular cartilage. "In terms of spinal effects, EGCG decreases TNF-α expression in the spinal cord in mouse models of bone cancer-caused pain and reduces glial cell activation via inhibition of fatty acid synthase (FASN), Ras homologue gene family member A (RhoA), and TNF-α in a model of spinal cord injury (SCI)." (PMID 32050623, 2020). "Additionally, it can bind fatty acid synthase and thus limit the spread of some bone cancers." (PMID 26355751, 2015).
cholangiocarcinoma (4 papers, 2021 to 2024). A carcinoma that arises from the intrahepatic biliary tree (intrahepatic cholangiocarcinoma) or from the junction, or adjacent to the junction, of the right and left hepatic ducts (hilar cholangiocarcinoma). "In cholangiocarcinoma, the knockdown of FASN suppresses cell growth, migration, and invasion, which is associated with decreased cellular levels of palmitic amide, a fatty acid amide derived from palmitic acid." (PMID 38060103, 2023). "RNA-sequencing was performed and verified that SKA3 enhanced fatty acid synthesis by up-regulating the expression of key fatty acid synthase, thus promoting cholangiocarcinoma cell proliferation under hypoxic conditions." (PMID 37821935, 2023). "Additionally, FASN knockdown would inhibit the proliferation, migration, and invasion of cholangiocarcinoma (CCA) cells, which are KKU055 and KKU213, and induced cell cycle arrest and apoptosis in CCA cell lines." (PMID 39584783, 2024).
clear cell renal cell carcinoma (4 papers, 2020 to 2025). "We verified survival related fatty acid genes in caki-1 cell and 786-0 cell (two human renal clear cell carcinoma cell lines) in two ways: down-regulating FASN expression and exposure to pharmacological inhibitor of FASN." (PMID 36516496, 2022). "We found a few studies providing deep analysis of the role of FASN in clear cell renal carcinoma development." (PMID 36516496, 2022). "This study investigated fatty acid synthase (FASN) mRNA expression in anthropometric adipose tissue and elucidated the prognostic value and potential mechanism of clear cell renal cell carcinoma (ccRCC)." (PMID 33569391, 2020). "The study by Xu and team found that FASN expression was positively correlated with aggressive cell proliferation, migration, apoptosis and lipid droplet formation and regulated metabolic disorders in clear cell renal carcinoma microenvironment." (PMID 36516496, 2022). "Furthermore, in clear-cell renal-cell carcinoma (ccRCC), there is an increased expression of stearoyl coenzyme a desaturase 1 (SCD1), fatty acid synthase (FASN), and acetyl coenzyme a carboxylase (ACC)." (PMID 39126035, 2024).
Hypoglycemia (4 papers, 2012 to 2024). A decreased concentration of glucose in the blood. "Mouse with liver-specific FASN knockout exhibited hypoglycemia and fatty liver, both of which were ameliorated upon the introduction of a dietary fat regimen." (PMID 38693536, 2024). "The liver-specific FASN knock-out (FASKOL) mice even developed hypoglycemia and fatty liver on a zero-fat diet, which was reasoned as the interference of PPARα activation, disruption of the transcription of genes critical for fatty acid oxidation, as well as interfered gluconeogenesis." (PMID 35052685, 2021). "The Zip14−/− phenotype included greater body fat, hypoglycemia and higher insulin levels, as well as increased liver glucose and greater phosphorylation of the insulin receptor and increased GLUT2, SREBP-1c and FASN expression." (PMID 23110240, 2012). "The direct inhibition of FASN might trigger chronic on-target safety risks due to the reduced β-oxidation of fatty acids by compromising the activity of PPARα, since FASKOL mice showed lipid accumulation and hypoglycemia with a zero-fat diet or fasting." (PMID 35052685, 2021). "Nonobese mice with hepatocyte-specific FASN deficiency (HKO mice) that were fed a zero-fat diet (ZFD) containing a high proportion of sucrose (62% by weight), but not those fed normal chow, developed aggravated NAFLD (despite impairment of DNL) as well as hypoglycemia due to impaired FAO." (PMID 37681411, 2023).
invasive breast carcinoma (4 papers, 2014 to 2025). A carcinoma that infiltrates the breast parenchyma. "In a previous study, we reported that a majority of clinically HER2-positive tumors were scored as FASN overexpressors in a series of almost 200 patients with invasive breast carcinoma." (PMID 33800852, 2021). "Particularly, in a cohort of 189 patients with invasive breast carcinoma, 85% of HER2 + tumors were scored with high FASN expression." (PMID 40133809, 2025). "To extend our previous in vitro observations, we analyzed breast tissue sections from invasive breast cancer patients for the presence of OPG, FASN and PGE2 by immunofluorescence staining." (PMID 27270654, 2016).
malignant glioma (4 papers, 2016 to 2024). A grade III or grade IV glioma arising from the central nervous system. "Lipid droplets then activated SREBP-1, which was overexpressed in malignant glioma cells and can initiate angiogenesis and the synthesis of lipids on cell membrane and organelle via fatty acid synthase (FASN)." (PMID 34211978, 2021). "We further found that FASN was expressed in all cultured malignant glioma cell lines that we analyzed." (PMID 32178271, 2020). "In this context, it should be noted that FABP7, which is highly expressed in malignant glioma and GSCs, showed similar expression pattern with that of FASN during the process of GSC differentiation as shown in the present study." (PMID 26808816, 2016). "In order to analyze whether FASN can be detected in EVs that circulate in the bloodstream of patients with malignant gliomas, we purified EVs from patient plasma and from the plasma of healthy donors and analyzed the EV lysates by Western blotting." (PMID 32178271, 2020). "Interestingly, FASN is also a potential drug target for the treatment of malignant gliomas." (PMID 32178271, 2020). "We first analyzed the expression of FASN in malignant gliomas compared to normal non-tumorous brain tissue." (PMID 32178271, 2020).
mantle cell lymphoma (4 papers, 2012 to 2025). Mantle cell lymphoma is a rare form of malignant non-Hodgkin lymphoma affecting B lymphocytes in the lymph nodes in a region called the ``mantle zone''. "We here report that FASN is highly and consistently expressed in mantle cell lymphoma (MCL), an aggressive form of B-cell lymphoid malignancy." (PMID 22485149, 2012).
metastatic melanoma (4 papers, 2014 to 2025). A melanoma that has spread from its primary site to another anatomic site. "Cutaneous malignant melanoma and metastatic melanoma over-express fatty acid synthase (FASN), which converts dietary carbohydrates to long-chain saturated fatty acids from acetyl-CoA, malonyl-CoA and NADPH." (PMID 34068792, 2021). "Elevation of intracellular calcium and ROS levels have also been reported to be mediators of the FASN inhibitor on inhibition of FASN activity and induction of apoptosis in mouse metastatic melanoma cell line B16-F10." (PMID 25255125, 2014).
multiple myeloma (4 papers, 2012 to 2022). "It has been demonstrated that FASN is highly expressed in bone marrow samples of patients with multiple myeloma, as demonstrated by Wang and colleagues." (PMID 29342092, 2018). "Fatty acid synthase is overexpressed in multiple myeloma, a malignancy of the mature B-cell lineage, although changes in the DLBCL subtypes are unknown." (PMID 35749395, 2022). "Wang’s group also demonstrated that treating multiple myeloma cell lines highly expressing FASN with cerulenin, an inhibitor of FASN, inhibited its activity and induced apoptosis, suggesting that FASN can be a potential target in the treatment of multiple myeloma." (PMID 29342092, 2018).
pancreatic ductal adenocarcinoma (4 papers, 2018 to 2024). An infiltrating adenocarcinoma that arises from the epithelial cells of the pancreas. "Notably, a high expression of FASN has been linked to poor prognosis of pancreatic ductal adenocarcinoma patients and depends heavily on induction of EGFR/ERK signalling." (PMID 29385093, 2018). "For example, activated epidermal growth factor receptor (EGFR) was shown to upregulate FASN in pancreatic ductal carcinoma and reciprocally, silencing or inhibition with small molecule inhibitor Erlotinib abolished FASN upregulation." (PMID 35323656, 2022).
prostate adenocarcinoma (4 papers, 2020 to 2023). "Downregulation of FASN with the RNAi technology has a significant impact on lipid metabolism depression and TG storage of human lymph node metastatic lesion of prostatic adenocarcinoma (LNCaP) cells." (PMID 32155177, 2020).
rectal cancer (4 papers, 2022 to 2025). A primary or metastatic malignant neoplasm that affects the rectum. "Our analysis revealed an upregulation of FASN expression in patients with both colon adenocarcinoma and rectal cancer, thereby providing preliminary support for our hypothesis." (PMID 40901481, 2025). "In rectal cancer, PITPNC1 can regulate the expression of CD155 via FASN, suppress CD8+ T-cell immune function, and enhance radiation resistance in rectal cancer." (PMID 40217455, 2025). "Our data confirm robust FASN expression in CRC, including colon adenocarcinoma, rectal cancer, and CRC cell lines." (PMID 40901481, 2025). "PITPNC1 regulates the expression of CD155 through FASN, inhibits CD8+ T cell immune function, and promotes radioresistance in rectal cancer." (PMID 38291470, 2024).
sarcoma (4 papers, 2020 to 2025). A usually aggressive malignant neoplasm of the soft tissue or bone. "Finally, a prognostic model for sarcoma patients was constructed using six hub genes: risk score = 0.05 × VEGFA + 0.25 × HMGB3 + 0.22 × FASN + 0.40 × RCC1 + 0.46 × NETO2-0.10 × BIRC5." (PMID 38240704, 2024). "Notably, expression of fatty acid synthase (FASN), a key enzyme in de novo lipogenesis, has been proposed as a prognostic marker in soft tissue sarcomas, further supporting the relevance of fatty acid metabolism in sarcoma progression and potential therapeutic targeting." (PMID 40710368, 2025). "As far as we know, the function of HMGB3, FASN and RCC1 in sarcoma has not been reported." (PMID 38240704, 2024).
alcoholic liver diseases (3 papers, 2021 to 2025). A disorder caused by damage to the liver parenchyma due to alcohol consumption. "SREBP1 plays a critical role in alcoholic liver disease, and it could regulate the transcription of downstream signaling, such as FASN, SCD, and ACLY." (PMID 34690775, 2021).
Alzheimer disease (3 papers, 2018 to 2025). A progressive, neurodegenerative disease characterized by loss of function and death of nerve cells in several areas of the brain leading to loss of cognitive function such as memory and language. "FASN is related to Alzheimer’s disease-related toxicity that modulates lipid peroxidation and induces ferroptosis." (PMID 38228715, 2024). "Given the capability of FASN to impair HSV-1 infectivity, we reasoned that targeting lipid metabolism may constitute an innovative approach to reduce the risk of virus reactivation, an especially critical concern in the context of neurodegenerative diseases, such as Alzheimer’s disease (AD)." (PMID 40327680, 2025).
Anorexia (3 papers, 2012 to 2025). Lack of desire to eat (loss of appetite). "Inhibitors of Fatty Acid Synthase (FASN) such as cerulenin or C75 are known to cause anorexia and significant body weight loss." (PMID 40541585, 2025). "Tamoxifen-induced anorexia in rats was associated with fatty acid synthase inhibition in the ventromedial nucleus of the hypothalamus and accumulation of malonyl-CoA." (PMID 23231648, 2012). "•FASN deletion in POMC neurons causes anorexia and adiposity reduction." (PMID 40541585, 2025). "However, FASN inhibitors have been shown to induce severe anorexia and weight loss, significantly limiting their clinical application potential." (PMID 24069385, 2013).
astrocytoma (3 papers, 2023 to 2025). "These compounds induced SREBF1 but not SREBP1c-mediated lipogenic genes such as SCD1, ACACA and FASN in HepG2 cells or astrocytoma cells." (PMID 36674804, 2023).
B-cell lymphoma (3 papers, 2017 to 2025). "Our results also demonstrate that B-cell lymphoma cells overexpressing PCLP1 rely on FASN activity to proliferate, which correlates with a previous study reporting up-regulated expression and activity of FASN in these tumor cells." (PMID 29245936, 2017). "Raji-PCLP1 cells treated with cerulenin, a FASN inhibitor, experienced a suppression in proliferation compared to Raji-Ctrl cells, suggesting that PCLP1-induced B-cell lymphoma cell proliferation relies on endogenous fatty acid synthesis." (PMID 29245936, 2017).
cervical squamous cell carcinoma (3 papers, 2021 to 2024). A squamous cell carcinoma arising from the cervical epithelium. "Fatty acid synthase expression is related to tumor-infiltrating immune cells in tumors (e.g., CD8+ T-cell infiltration level in cervical squamous cell carcinoma)." (PMID 34879004, 2021).
co-infection (3 papers, 2010 to 2016). "We evaluated serum FASN concentration in 191 consecutive HIV-infected patients in the absence or presence of HCV co-infection." (PMID 20707918, 2010). "Of note, co-infection with HCV further significantly increased serum FASN concentration." (PMID 20707918, 2010). "A recent study has revealed that co-infection with HIV and HCV enhances the release of fatty acid synthase into the circulation suggesting the enzyme is targeted specifically by HVC." (PMID 24957365, 2012). "FASN is also significantly up-regulated during infection with HCV, a frequent co-infection in HIV-patients." (PMID 20707918, 2010). "FASN, an intracellular protein, appears to exit cells during HIV infection and this release into the circulation is exacerbated in the presence of HCV co-infection, a condition that is frequently observed in HIV-infected patients." (PMID 20707918, 2010). "Moreover, serum alanine aminotransferase (ALT) values provided the best discrimination with respect to the presence or absence of HCV co-infection and correlated significantly with serum FASN concentration irrespective of the condition of co-infection." (PMID 20707918, 2010). "Moreover, the correlation between serum insulin and serum FASN was maintained irrespective of HCV co-infection or altered ALT values in HIV-infected patients." (PMID 20707918, 2010). "It is interesting to note that the co-infection of MDA-MB-231 cells by lentiviruses expressing FASN and miR-m15a-m16-1 did not markedly further increase FASN expression in MDA-MB-231 cells." (PMID 27713175, 2016). "Serum alanine aminotransferase (ALT) values correlated significantly with serum FASN concentration and provided the best discrimination with respect to the presence or absence of HCV co-infection." (PMID 20707918, 2010). "Serum fatty acid synthase concentration was found higher in HIV-infected patients than in healthy participants and HCV co-infected patients showed higher levels than those without co-infection." (PMID 24957365, 2012). "Serum FASN concentration was significantly higher in HIV-infected patients than in healthy participants and HCV co-infected patients showed higher levels than those without co-infection." (PMID 20707918, 2010).
colorectal tumors (3 papers, 2022 to 2025). "Investigations conducted on breast, pancreatic, hepatic, and colorectal tumors showed that FASN—fatty acid synthase, a protein that catalyzes the de novo synthesis of long-chain fatty acids—is strongly upregulated." (PMID 38672673, 2024).
Dengue (3 papers, 2009 to 2017). "Here, we found that a fatty acid synthase inhibitor (C75) that decreased the amount of LDs in DENV-infected and uninfected cells, also inhibited dengue replication 100 to 1000 fold." (PMID 19851456, 2009).